ABCC6 (ATP binding cassette subfamily C member 6)
Diseases named in the same sentence as ABCC6 in open-access papers (continued):
Sharing a sentence is not in itself a finding about the gene and the disease.
ABCC6 also shares sentences with these, for which no sentence is quoted: diabetes (3 papers); Cerebrovascular Disease (2); epilepsy (2); generalized arterial calcification of infancy 2 (2); Gronblad-Strandberg syndrome (2); Harlequin ichthyosis (2); heart failure (2); ichthyosis (2); nephrocalcinosis (2); neuroblastoma (2); osteoporosis (2); Parkinson’s (2); retinopathy (2); Tangier disease (2); acute kidney injury (1); albinism (1); angioid streaks (1); arterial disease (1); arteriosclerosis (1); brain tumour- (1); Cantú syndrome (1); cholestasis (1); choroidal neovascularization (1); chronic myeloid leukemia (1); colorectal tumor (1); congenital dyserythropoietic anemia (1); coronary stenosis (1); cutis laxa (1); cystinuria (1); Dubin-Johnson syndrome (1).
A further 49 diseases each share a sentence with ABCC6 in 1 paper.